PRMT1 (protein arginine methyltransferase 1)
Diseases named in the same sentence as PRMT1 in open-access papers (continued):
Sharing a sentence is not in itself a finding about the gene and the disease.
cardiovascular disease (8 papers, 2013 to 2025). "Beyond its pivotal function in oncology, the dysregulation of PRMT1 is also intricately associated with cardiovascular disorders." (PMID 41256732, 2025). "It is conceivable that Prmt1 ablation results in ER stress and unfolded protein responses through decreased myocardin expression associated with cardiovascular diseases." (PMID 34635781, 2021). "Basically, the involvement of PRMT1 in cardiovascular diseases is dependent on its post-translational activity on substrates." (PMID 37951845, 2023). "PRMT1 is the dominant type I PRMT and has an essential role in cell proliferation and genome maintenance and defects in PRMT1 are associated with cardiovascular disease." (PMID 27462403, 2016). "PRMT1 has a multifaceted and significant involvement in various critical aspects of cardiovascular disorders, including the survival and hypertrophy of cardiomyocytes, the proliferation of vascular smooth muscle cells (VSMCs), and the failure of endothelial function." (PMID 41256732, 2025). "Our present study demonstrates that PRMT1 relieves MH by methylating SRSF1, which is expected to provide a new theoretical basis for the pathogenic mechanism of MH and potential drug targets for reducing MH and associated cardiovascular disease." (PMID 39659162, 2024). "Although substantial evidence indicates that aberrant protein selective splicing is related to MH, in which SRSF1 is involved in cardiovascular disease by selectively splicing downstream signaling proteins, whether PRMT1 affects MH by regulating SRSF1 remains largely unknown." (PMID 39659162, 2024). "The targeted suppression of PRMT1 or the enhancement of ADMA breakdown, such as through the DDAH enzyme, has emerged as a significant research focus for enhancing endothelial function and preventing and treating cardiovascular disorders." (PMID 41256732, 2025).
hematological malignancies (5 papers, 2019 to 2023). "PRMT1, a type I arginine methyltransferase, has been reported to play an important role in the progression of various diseases, especially hematological diseases." (PMID 37558663, 2023). "Aberrant expression of PRMT1 is strongly correlated with poor outcomes of both solid tumors and hematologic malignancies." (PMID 37600810, 2023). "PRMT1 is the most predominant enzyme in the family and plays a multifaced roles in both normal hematopoiesis and hematological malignancies." (PMID 37600810, 2023). "Inhibitors directed against PRMTs type I, i.e., PRMT1, CARM1, PRMT5, and PRMT7, have been tested on hematological malignancy models and have shown a significant decrease in malignant cell proliferation and an increased apoptosis." (PMID 36358861, 2022).
metabolic disease (5 papers, 2022 to 2025). A congenital disorder (due to inherited enzyme abnormality) or acquired (due to failure of a metabolically important organ) disorder resulting from an abnormal metabolic process. "This again highlights the importance of a suitable model to analyze PRMT1 function and inhibition in metabolic diseases." (PMID 40001488, 2025). "The core of this review is dedicated to examining the mechanistic underpinnings of PRMT1 dysregulation in oncogenesis, metabolic disorders, and immune dysfunction." (PMID 41256732, 2025). "It further suggests a potential role of PRMT1 as a critical transcriptional cofactor in EECs specification and homeostasis to affect metabolism and metabolic diseases." (PMID 38835047, 2024). "Now that it has been revealed that PRMT1 may control AMPK as well, it makes PRMT1 all the more interesting to study in metabolic diseases." (PMID 40001488, 2025). "This suggests that PRMT1 signaling likely is involved in many different types of diseases and could potentially be an interesting target in metabolic diseases." (PMID 40001488, 2025). "However, recent in vitro and in vivo studies have highlighted that PRMT1 may also promote metabolic disorders." (PMID 40001488, 2025). "Consequently, pharmacological targeting of PRMT1 may offer a novel therapeutic avenue for the management of NAFLD and associated metabolic disorders." (PMID 41256732, 2025). "Overexpression of PRMT1 significantly promotes lipid accumulation through the CFLAR-JNK axis in mouse primary hepatocytes, while knockdown of PRMT1 alleviates this metabolic disorder in OA/PA-treated primary hepatocytes." (PMID 39063139, 2024).
renal diseases (3 papers, 2018 to 2025). "Key lysine and arginine methyltransferases under investigation for renal disease treatment include EZH2, G9a, DOT1L, PRMT1 and PRMT5." (PMID 35559246, 2022). "In general, we find that PRMT1 plays a role in kidney through ADMA synthesis or epigenetic gene regulation mediated by histone modification or even non-histone modification mediated transcription factors, and its role in renal diseases deserves further study." (PMID 35559246, 2022).
immune dysfunction (2 papers, 2017 to 2025). "PRMT1 is essential and has been recognized as a potential therapeutic target for immune disorders, despite the challenges involved." (PMID 41256732, 2025).
blood cancers (1 paper, 2025). "A study suggested that PRMT1 overexpression may inhibit differentiation and contribute to the development of blood cancers." (PMID 40612681, 2025).
cardiac diseases (1 paper, 2018). "Interestingly, heterozygous cKO mice exhibited a partial lethality at 6 months of age and a sensitivity to isoproterenol-induced cardiac defects, further supporting for the importance of reduced PRMT1 in cardiac diseases." (PMID 30504773, 2018).
head and neck tumors (1 paper, 2020). "Corroborating our observation, the expression of PRMT1 is upregulated in ESCC and head and neck tumors." (PMID 32872669, 2020).
inflammation (1 paper, 2019). Aberrant reaction of the microcirculation characterized by movement of fluid and leukocytes from the blood into extravascular tissues. "For example, in lung inflammation, RKIP is capable of regulating the cell type and signalling specific expression of the enzyme protein arginine methyltransferase 1 (PRMT1)." (PMID 31766768, 2019).
muscular disorders (1 paper, 2023). "Dysregulation of arginine methylations has been linked to pathomechanisms of several diseases, including neurodegeneration (i.e., PRMT1-ALS, PRMT5-PD), and muscular disorders." (PMID 37773136, 2023).
PRMT1 also shares sentences with these, for which no sentence is quoted: colorectal tumors (2 papers); leukopenia (2); acute promyelocytic leukemia (1); allergic asthma (1); Aortic dissection (1); arterial diseases (1); bacterial infection (1); benign tumors (1); breast (1); breast adenocarcinoma (1); cholangiocarcinoma (1); Cirrhosis (1); collecting duct carcinomas - Bellini (1); colon (1); endometrial cancer (1); esophageal tumor (1); Glucose intolerance (1); Immunodeficiency (1); infectious disease (1); lung adenocarcinoma (1); male infertility (1); metastatic melanoma (1); Miscarriage (1); monoclonal gammopathy of undetermined significance (1); non-alcoholic fatty liver disease (1); Nonalcoholic Steatohepatitis (1); ovarian serous carcinoma (1); ovarian tumor (1); pancreatic adenocarcinoma (1); prostate tumor (1).
A further 16 diseases each share a sentence with PRMT1 in 1 paper.